SPATA31C1 (SPATA31 subfamily C member 1)
Description:
May play a role in spermatogenesis.
Synonyms: FAM75C1; FLJ36055
Tractability: Antibody: UniProt predicts a signal peptide or a membrane-spanning region.
Gene: Protein-coding gene on chromosome 9 (87,914,488 to 87,923,657, forward strand). Ensembl gene ENSG00000230246.
Subcellular location: Membrane
Gene Ontology:
Cellular component: membrane
Homologues: Orthologues: rat Spata31 (26% identical), mouse Spata31 (25% identical). Paralogues in human: SPATA31C2 (94% identical), SPATA31A1 (86% identical), SPATA31A3 (86% identical), SPATA31A6 (86% identical), SPATA31A7 (86% identical), SPATA31A5 (86% identical), SPATA31E1 (34% identical), SPATA31D1 (27% identical), SPATA31D3 (16% identical), SPATA31D4 (16% identical), SPATA31F1 (15% identical), SPATA31F3 (2% identical).